BRCA1 (BRCA1 DNA repair associated)
Diseases named in the same sentence as BRCA1 in open-access papers (continued):
Sharing a sentence is not in itself a finding about the gene and the disease.
tumor (continued). "Tumor WES derived analysis from the single CRC from person 009 demonstrated that tumorigenesis was dominated by the BRCA1 variant-related HRD process, evidenced by the high proportion of HRD-related SBS3 and ID6 mutational signatures." (PMID 38063999, 2024). "Of 52 tumor samples from the population evaluable by FoundationOne®CDx, 39 (75.0%) and 13 (25.0%) patients exhibited BRCA1 and BRCA2 mutations, respectively; 1 (1.9%) patient exhibited mutations in both genes; and 1 (1.9%) patient had mutations in neither." (PMID 38869771, 2024). "Specific parameters, including the tumor microenvironment, immune cells, immune checkpoint molecules, BRCA1/2 mutations, genetic oncology, and prognosis, help identify patients eligible for immunotherapy." (PMID 38543119, 2024). "The prognostic value of sTILs remained across patients with different BRCA1 status, albeit this association was stronger in those with tumor BRCA1-PM." (PMID 38191387, 2024). "miR-664b-3p was found to enhance apoptosis (programmed cell death) by regulating the levels of BRIP1, which is a protein that interacts with BRCA1 (a tumor suppressor gene commonly associated with BC)." (PMID 38832155, 2024). "PARP inhibitors increase DNA damage in BRCA1/2-deficient tumor cells, preventing repair and thereby increasing cell death, a phenomenon called synthetic lethality." (PMID 39528473, 2024). "This suggests that low RFWD3 expression can influence tumour genotype in a similar way to mutation of FA genes including BRCA1 and BRCA2." (PMID 38711848, 2024). "This association was significantly larger in tumor BRCA1-PM patients, as was reflected by a significant interaction term between sTILs and tumor BRCA1-PM (HRinteraction, 0.82; 95% CI, 0.68–0.98)." (PMID 38191387, 2024). "Analyzing BRCA1/2 tumor pathogenic variants (TPVs) in epithelial tubal/ovarian cancers (EOCs) has become an essential part of the diagnostic workflow in many centers to guide treatment options and genetic cascade testing." (PMID 38730634, 2024). "A notable example of such an SL target gene pair is PARP and BRCA1/2, where BRCA1/2 loss of function mutations sensitize tumor cells to pharmacological inhibition of PARP." (PMID 38886830, 2024). "For instance, in tumors with pathogenic BRCA1 mutations associated with hormone receptor positivity, hormone therapy (tamoxifen and aromatase inhibitors) delays tumor progression, reduces risk significantly, and prevents the onset of contralateral tumors." (PMID 39796670, 2024). "Somatic BRCA mutations were defined as either a BRCA1 or BRCA2 mutation present only in the tumor tissue." (PMID 38540206, 2024). "Because tumour cells with deficient homologous repair mechanisms are more sensitive to PARPi, including tumours with BRCA1/2 mutations and BRCAness, we analysed mutations in a panel of 69 genes involved in DNA repair." (PMID 38213724, 2024). "BRCA1 promoter methylation is a common occurrence in TNBCs, leading to a tumor phenotype resembling that of BRCA1-mutated tumors." (PMID 39744000, 2024). "TNBC shares histological features with germline BRCA1-associated tumours, with lower levels of adenine, N6-methyladenosine, and 1-methyladenosine in patients with BRCA1 mutations." (PMID 39791706, 2024).
tumor (continued). "For example, Niraparib is a selective PARP-1 and PARP-2 inhibitor with favorable pharmacokinetics and anti-tumor roles in patients with BRCA1/2 mutations." (PMID 39588300, 2024). "Inherited defects in DNA repair genes, such as BRCA1/2 in breast, ovarian and prostate cancers, significantly increase the risk of tumor development." (PMID 38750579, 2024). "The overall percent agreement for ctDNA and tumour samples to detect BRCA1/2 and HRR mutations was 94.8% (95% CI: 91.9–97.8) and 91.5% (95% CI: 87.8–95.3), respectively." (PMID 38755585, 2024). "The tumor suppressor genes BRCA1/2 and their encoded proteins are important elements of DNA double-strand break repair by homologous recombination." (PMID 38577595, 2024). "Termed tumor suppressor genes, BRCA1 and BRCA2, when harboring specific deleterious variants or mutations, confer a predisposition to carcinogenesis." (PMID 38809921, 2024). "Although BRCA1 mutation carriers rarely develop ER+ tumors, in our model, tumors were heterogenous with a fraction of tumor cells expressing ERα and GATA3." (PMID 38059556, 2024). "In BRCA1 gene-deficient breast cancer, PARPi also upregulates PD-L1 expression on tumor cell surfaces by inactivating GSK3β, thereby inhibiting the activation of tumor-infiltrating T lymphocytes." (PMID 38762484, 2024). "This means that every 10% sTIL increment was associated with a 31% increase in OS for tumor BRCA1-PM patients and a 16% increase for patients with other BRCA1 status." (PMID 38191387, 2024). "Since BRCA1/2-mutant tumor cells are deficient in HR-mediated DNA repair, they are especially reliant on PARP1/2 for their survival." (PMID 38956205, 2024). "Except for MINAS caused by variants in BRCA1/2, information on the possible implications of combinations of PVs in other genes for the risk of developing tumours is limited." (PMID 39021548, 2024). "Currently, BRCA1/2 mutations are the most established biomarkers for PARPi resistance, and germline and tumour testing are recommended for OC patients at diagnosis." (PMID 38374229, 2024). "The PARPi exhibit synthetic lethality to selectively kill tumor cells with HR deficiency, with BRCA1/2 mutations being the most significant pathogenic mutations in HRR related-genes." (PMID 39333482, 2024). "This is an unexpected finding since SBS3-associated mutations induced by BRCA1/2-deficiency would be accumulating in a cell line or tumor during the tumorigenesis process and remain in the genome even after reversal of the HRD phenotype." (PMID 38398132, 2024). "The SBS3 signature, which was strongly associated with germline and somatic BRCA1/2 mutations and BRCA1 methylation in other studies, was seen in our study in only two samples; however, both were obtained from BRCA1/2 germline and tumor wild-type patients." (PMID 38927686, 2024). "As the prediction mainly relies on hematoxylin and eosin (HE)-stained tumor slides, the underlying idea is that both BRCA1/2 mutations and HR deficiency have phenotypical consequences at a histological level that can be detected from digital images." (PMID 39220639, 2024). "PARPi significantly alters the therapeutic landscape of tumours with genetic defects, such as BRCA1 and BRCA2 mutations, which are primarily involved in the homologous repair of DNA damage." (PMID 39690136, 2024). "For this patient, sotorasib was recommended by the molecular tumor board, but treatment with olaparib was initiated due to concurrent BRCA1/2 mutations." (PMID 38664720, 2024). "In contrast to the significant decrease in the number of Flag-expressing Brca1-deficient tumor cells, the number of Gata3-expressing Brca1-deficient tumor cells was insignificantly changed in response to OLA." (PMID 38627785, 2024).
tumor (continued). "Family history as a risk factor is mainly due to the association with BRCA1 mutations, which have been identified as contributors to the metastatic and aggressive nature of tumor cells." (PMID 38300959, 2024). "Almost all of the tumor models, either BRCA1/2 deficient (UWB1.289, HCC1937, Capan‐1) or PTEN deficient (U251, PC3), were profoundly sensitive to thioparib." (PMID 36652375, 2023). "Although patients with germline mutations in BRCA1/2 are defined as harboring an HRD tumor phenotype, there is a group of approximately 20% of patients that present a positive HRD status based on tumor genomic analyses." (PMID 37958189, 2023). "BRCA1/2 pathogenic variant were identified in 24% of acftDNA samples and for those with matching tumor NGS results." (PMID 37932736, 2023). "Overall, somatic predicted protein truncating variants in BRCA1/2 were found in 7% (n = 85) of tumours and 2% (n = 21) had a predicted protein truncating variant detected in one of the other 11 HR-related genes." (PMID 36805919, 2023). "In our current study, tumor BRCA1/2 deleterious variants were identified in 31.2% of HGOCs, one quarter of these mutations are somatic." (PMID 36922847, 2023). "We found residual BRCA1 gene expression associated to incomplete (mono-allelic) promoter methylation in different HRD tumours in the resistant and stable disease groups." (PMID 37029129, 2023). "HRR is a BRCA1/2 gene-dependent repair mechanism, and therefore, tumor cells carrying BRCA1/2-deficient genes cannot repair DNA damage through the HRR, and requiring PARP proteins for the restoration of SSBs." (PMID 37152924, 2023). "With the used methylation assay, tumor BRCA1 promoter hypermethylation and a germline BRCA1 mutation seem mutually exclusive." (PMID 36112334, 2023). "TNBC is a heterogeneous disease, with a substantial percentage of tumours showing homologous recombination deficiency (HRD) as a result of mutations in the BRCA1 and BRCA2 genes." (PMID 37029129, 2023). "These four all revealed the low-level BRCA1 methylation in their tumor biopsies to share the same magnitude and allele specificity as the methylation in the matched WBCs (red dots)." (PMID 38053165, 2023). "Pyridostatin has been reported to exert an anti-tumor effect through its G-quadruplexes binding activity, and has been shown to exert a highly specific activity against BRCA1/2-deficient tumors." (PMID 36899366, 2023). "The genetic deletion of RANK in the mammary epithelium or the inhibition of RANKL in Brca1-deficient mice substantially delayed hyperplasia and tumor onset." (PMID 37568820, 2023). "Remarkably, a single low dose of 10 μmol/kg PEG-Exa—only approximately 0.2 μmol/mouse—caused complete suppression of tumor growth of BRCA1-deficient MX-1 xenografts lasting over 40 days." (PMID 37377899, 2023). "Our patient’s BRCA1 mutation VAFs suggest that this molecular event was acquired relatively early in the evolution of this tumor, which is also supported by the high HRD scores at both primary site and metastasis." (PMID 37980380, 2023). "Unsurprisingly, germline BRCA1/2 pathogenic variants were the most frequently detected HRR mutations in women with GIS-positive tumours." (PMID 36765687, 2023). "(2011) showed that women BRCA-mutated with BC frequently developed type-2 diabetes, probably because the mutation induces the loss of BRCA1 anti-tumor activity, leading to an over-activation of IGF-IR signaling pathway." (PMID 37081976, 2023).
tumor (continued). "In essence, BRCA1/2 mutations significantly impact early BC by shaping tumor traits, treatment responses, and long-term risk management." (PMID 38001690, 2023). "The only germline BRCA1/2 mutation reported in a patient aged ≥80 was detected in both germline and tumour DNA." (PMID 36765687, 2023). "The only patient diagnosed with a germline BRCA1/2 pathogenic variant aged ≥80 had a small deletion (four base pairs in size) in BRCA2 that was detected first in tumour DNA and then subsequently in germline DNA." (PMID 36765687, 2023). "Stromal-specific BRCA1 depletion causes tumor growth by inducing HIF-1a levels, increasing the ketone body, and activating autophagy/mitophagy." (PMID 38067169, 2023). "Combination treatment with olaparib and the ALDH1A1 inhibitor is able to synergistically reduce tumor cell viability in the PDOs with mutated BRCA1/2 and positive ALDH1A1 expression." (PMID 37429899, 2023). "With only 3.3% of non-contributive test results, shallowHRDv2 robustness is similar to other genetic testing in clinical routine, such as BRCA1/2 tumor mutation testing, which showed a 4.4% failure rate in the PAOLA-1 clinical trial." (PMID 37945748, 2023). "After 2 years, olaparib treatment prevented tumor development in 22.1% of patients with chemotherapy-responsive BRCA1/2-mutated malignancies." (PMID 37035242, 2023). "The combination therapy of cisplatin and PD-1 significantly enhanced the anti-tumor immunity of BRCA1-deficient mice, resulting in a strong systemic and intratumoral immune response." (PMID 37350936, 2023). "Case 15230 with BRCA1-mutated HGSC was found to have a missense TP53BP1 p.Lys1141Gln variant at a VAF of 46% in the post-PARPi tumour sample." (PMID 38072854, 2023). "Breast cancer susceptibility gene 1 (BRCA1) is an important tumor suppressor gene, as mutations of BRCA1 are associated with 20%–30% of familial breast and ovarian cancers." (PMID 37789001, 2023). "Tumor cells that carry BRCA1/2 variants are dysfunctional in the homologous recombination repair pathway." (PMID 37662839, 2023). "The three germline BRCA1/2 variants missed using our in-house tumour BRCA1/2 assay included BRCA1 Exon 13 duplication, BRCA2 Exon 1–2 deletion and BRCA2 Exon 14–16 deletion." (PMID 36765687, 2023). "Two patients had a tumor with a BRCA1 mutation, one had BRCA1 and FANCA mutations, one had a PALB2 mutation, one had a BRCA1 VUS, and one had a BRCA2 VUS." (PMID 37173992, 2023). "Promoter hypermethylation of BRCA1 likely explains BRCA-deficiency in two of these tumours (tumour 10 and 37)." (PMID 37316882, 2023). "None of the patients with germline BRCA1 pathogenic variants revealed either WBC or tumor BRCA1 methylation." (PMID 38053165, 2023). "CX-5461 was also recently shown to decrease cell viability in ATRX-deficient glioma and BRCA1/BRCA2-deficient tumor cells." (PMID 36770824, 2023). "This approach provides an opportunity to target tumors with mutations in tumor suppressor genes such as BRCA1, BRCA2, and RAD51, where loss of function results in the tumorigenic consequences of deficient homologous recombination." (PMID 37628794, 2023). "BRCA loss, particularly Brca1−/−, resulted in increased tumor death following treatment with exogenous formaldehyde." (PMID 37196082, 2023). "The separation from the non-BRCA1/BRCA2 tumours is mainly driven by homologue repair deficiency (HRD), i.e. the HRD-associated substitution signature (SBS) 3, where a higher level is detected in the BRCA1/BRCA2-mutated tumours." (PMID 37316882, 2023).
tumor (continued). "As only half of BD cases harbored germline BRCA1/2 variants, our results support the superiority of testing approaches involving tumor tissue analysis in detecting potentially actionable alterations." (PMID 36900320, 2023). "The efficacy results were positive for several cohorts, including olaparib in various tumor types with BRCA1/2-inactivating mutations and palbociclib in CDK4-amplified STS, and they were negative for seven cohorts." (PMID 37998367, 2023). "PARPis significantly extended PFS with underlying BRCA1/2 mutation in the germline and tumor (somatic) compared to BRCA1/2-negative HGSOC, so patients with HGSOC benefit from BRCA1/2 mutation and HRD positivity." (PMID 38001616, 2023). "The majority of these tumours showed either BRCA1 mutation or methylation (63%) and improved benefit from platinum-based chemotherapy compared to conventional chemotherapy (Hazard Ratio—0.12, p = 0.006)." (PMID 36831687, 2023). "BRCA1/2 mutation carriers whose tumors displayed expression of nFTH1 more frequently had a favorable tumor grade (p = 0.015) as well as positive ER (p = 0.002) and PR status (p = 0.029)." (PMID 38201455, 2023). "This testing model relies on tumour BRCA1/2 tests being able to detect all types of pathogenic variant." (PMID 38201604, 2023). "In vitro studies of PARP inhibitors show a significant anti-tumour response dependent on BRCA1/2 deficiency, activation of the cGAS/STING pathway and recruitment of CD8+ T cells." (PMID 36831687, 2023). "Its features include tumour heterogeneity, poor prognosis, and recurrence due to chemotherapy resistance mostly associated with germline BRCA1/2 mutations." (PMID 37873862, 2023). "A tumor DNA test, identifying germline and acquired pathogenic variants in BRCA1/2 and other OC risk genes, functions as an efficient prescreen to tailor genetic counseling to patients at higher risk of hereditary cancer." (PMID 35570228, 2023). "In those patients who underwent tumour and germline testing, 15.3% (56/367) had a BRCA1/2 pathogenic variant (36 germline and 20 somatic)." (PMID 38201604, 2023). "Clinicopathological patient characteristics were obtained from medical records, and formalin-fixed paraffin-embedded tissue specimens were analyzed for histological markers, mutations of 126 genes, BRCA1 methylation, and stromal tumor-infiltrating lymphocytes." (PMID 36494460, 2023). "There is limited real-world data reporting the number of germline BRCA1/2 pathogenic/likely pathogenic variants missed by testing tumour DNA using commercially available clinically validated genetic assays." (PMID 38201604, 2023). "Carrying BRCA1/2 mutations, earlier stage, and lower levels of residual tumor after surgery have been proven as predictors of better prognosis for patients receiving platinum chemotherapy in ovarian cancer." (PMID 37193789, 2023). "By contrast, only 3% (1/31) of patients with a germline BRCA1/2 pathogenic variant had a GIS-negative tumour (p = 0.002)." (PMID 36765687, 2023).